SLC35A5 (solute carrier family 35 member A5)
Description:
Probable UDP-sugar:UMP transmembrane antiporter involved in UDP-alpha-D-glucuronate/UDP-GlcA, UDP-GlcNAc/UDP-N-acetyl-alpha-D-glucosamine and UDP-N-acetyl-alpha-D-galactosamine/UDP-GalNAc transport from the cytosol to the lumen of the Golgi.
Synonyms: FLJ20730
Tractability: Antibody: UniProt predicts a signal peptide or a membrane-spanning region.
Gene: Protein-coding gene on chromosome 3 (112,561,269 to 112,587,350, forward strand). Ensembl gene ENSG00000138459.
Subcellular location: Golgi apparatus membrane
Subcellular location (Human Protein Atlas): Golgi apparatus
Gene Ontology:
Molecular function: protein binding; pyrimidine nucleotide-sugar transmembrane transporter activity
Biological process: nucleobase-containing compound transport; organophosphate ester transport; pyrimidine nucleotide-sugar transmembrane transport
Cellular component: Golgi membrane; membrane
Genetic constraint (gnomAD): Loss-of-function variants: 21 observed, 31.33 expected, observed/expected ratio (o/e) 0.67, 90% interval 0.47 to 0.96. The upper end of that interval is the gene's LOEUF score, 0.96, which puts it in group 4 of 6, group 1 being the genes least tolerant of losing a copy. Missense variants: 481 observed, 485.4 expected, observed/expected ratio (o/e) 0.99, 90% interval 0.92 to 1.07. Synonymous variants: 176 observed, 171.28 expected, observed/expected ratio (o/e) 1.03, 90% interval 0.91 to 1.16.
Homologues: Orthologues: chimpanzee SLC35A5 (99% identical), macaque SLC35A5 (96% identical), dog SLC35A5 (91% identical), guinea pig SLC35A5 (88% identical), pig SLC35A5 (88% identical), rabbit SLC35A5 (87% identical), mouse Slc35a5 (86% identical), rat Slc35a5 (84% identical), tropical clawed frog slc35a5 (56% identical), zebrafish slc35a5 (56% identical), Drosophila melanogaster senju (17% identical). Paralogues in human: SLC35A3 (22% identical), SLC35A2 (21% identical), SLC35A1 (19% identical), SLC35A4 (16% identical).
Diseases named in the same sentence as SLC35A5 in open-access papers:
SLC35A5 is named in the same sentence as 3 diseases in open-access papers, as found by Europe PMC text mining. Sharing a sentence is not in itself a finding about the gene and the disease. The quoted sentences say what the papers report.
colorectal cancer (1 paper, 2025). A primary or metastatic malignant neoplasm that affects the colon or rectum. "Both SLC35A4 and SLC35A5 consistently exhibited lower expression in tumor tissues across all tissue types, including colorectal cancer." (PMID 40303483, 2025). "In our study, we observed that the expression of SLC35A4 and SLC35A5 is decreased in colorectal cancer compared to adjacent non-cancerous tissues." (PMID 40303483, 2025).
tumor (2 papers, 2021 to 2025). "In contrast, the other family members, including SLC35A1, SLC35A3, SLC35A4, and SLC35A5, demonstrated lower expression in tumor tissues." (PMID 40303483, 2025). "The results revealed that the expressions of SLC35A1 and SLC35A5 were negatively correlated with tumor purity (p < 0.05)." (PMID 40303483, 2025).
SLC35A5 also shares sentences with these, for which no sentence is quoted: neurological diseases (1 paper).